IRX2 (iroquois homeobox 2)
Synonyms: IRXA2
Tractability: No criterion of Open Targets' tractability assessment is met for any kind of drug.
Gene: Protein-coding gene on chromosome 5 (2,741,794 to 2,751,677, reverse strand). Ensembl gene ENSG00000170561.
Subcellular location: Nucleus
Subcellular location (Human Protein Atlas): Nucleoli; Nucleoplasm
Pathways (Reactome):
Developmental Biology: Nephron development
Gene Ontology:
Molecular function: DNA-binding transcription repressor activity, RNA polymerase II-specific; protein binding; sequence-specific DNA binding; DNA-binding transcription factor activity, RNA polymerase II-specific; RNA polymerase II cis-regulatory region sequence-specific DNA binding; DNA binding
Biological process: negative regulation of transcription by RNA polymerase II; cell development; neuron differentiation; regulation of transcription by RNA polymerase II; metanephros development; proximal/distal pattern formation involved in metanephric nephron development; regulation of DNA-templated transcription; specification of loop of Henle identity
Cellular component: chromatin; nucleus
Genetic constraint (gnomAD): Loss-of-function variants: 26 observed, 27.64 expected, observed/expected ratio (o/e) 0.94, 90% interval 0.69 to 1.3. The synonymous counts are far from expectation, so gnomAD's model fits this gene poorly and the ratio says little. Missense variants: 782 observed, 566.5 expected, observed/expected ratio (o/e) 1.38, 90% interval 1.3 to 1.46. Synonymous variants: 424 observed, 285.72 expected, observed/expected ratio (o/e) 1.48, 90% interval 1.37 to 1.61.
Homologues: Orthologues: chimpanzee IRX2 (99% identical), macaque IRX2 (96% identical), pig IRX2 (96% identical), guinea pig IRX2 (94% identical), dog IRX2 (94% identical), mouse Irx2 (92% identical), rat Irx2 (91% identical), tropical clawed frog irx2 (70% identical), zebrafish irx2a (65% identical), rabbit IRX2 (64% identical). Paralogues in human: IRX5 (48% identical), IRX3 (32% identical), IRX4 (31% identical), IRX1 (29% identical), IRX6 (28% identical), MKX (16% identical).
Diseases named in the same sentence as IRX2 in open-access papers:
IRX2 is named in the same sentence as 42 diseases in open-access papers, as found by Europe PMC text mining. Sharing a sentence is not in itself a finding about the gene and the disease. The quoted sentences say what the papers report.
breast cancer (7 papers, 2015 to 2023). A primary or metastatic malignant neoplasm involving the breast. "In breast cancer, low expression of IRX2 has been observed and shown to be associated with the presence of disseminated tumor cells." (PMID 30760827, 2019). "Low IRX2 was also associated with shortened survival of breast cancer patients in one analyzed breast cancer data set." (PMID 26560478, 2015). "Loss of IRX2 expression could therefore contribute to early hematogenous dissemination of breast cancer by sustaining chemokine secretion and enabling mobilization of tumor cells." (PMID 26560478, 2015). "Therefore, we rather stably expressed a c-terminal HA-tagged IRX2 protein in IRX2-deficient BT-549 and Hs578t breast cancer cell lines of basal subtype." (PMID 26560478, 2015). "We have recently shown that low IRX2 expression is associated with the presence of DTCs in the bone marrow of breast cancer patients, suggesting a possible role of IRX2 as a metastasis suppressor protein in breast cancer." (PMID 26560478, 2015). "To experimentally validate the possible role of IRX2 as a metastasis suppressing protein and repressor of migration and chemokine expression, we stably expressed a c-terminal HA-tagged IRX2 protein in IRX2-deficient BT-549 and Hs578t breast cancer cell lines." (PMID 26560478, 2015). "Also in cell lines low IRX2 expression was associated with mainly basal breast cancer cell lines." (PMID 26560478, 2015). "IRX2 plays a significant role in lymph node metastasis of breast cancer, and its expression significantly increases in lymph node metastasis of breast cancer." (PMID 37664112, 2023). "In this study, we aimed to validate the clinical importance of IRX2 expression and to gain insights into the significance of IRX2 expression in the progression of breast cancer." (PMID 26560478, 2015). "IRX2 mRNA expression was detected in eight out of 11 breast cancer cell lines at variable levels, as determined by quantitative real-time PCR analysis." (PMID 26560478, 2015). "To assess the physiological relevance of IRX2 in breast cancer, we evaluated IRX2 expression in a large breast cancer cohort (n = 1992)." (PMID 26560478, 2015). "We furthermore found that the IRX2 protein inhibits cellular motility of breast cancer cells, supporting the presumptive metastasis suppressing function of the IRX2 protein." (PMID 26560478, 2015). "Overexpression of the IRX2 transcription factor in BT-549 and Hs578T breast cancer cells leads to concordant repression of CCL5, CXCL8 and CXCL10 mRNA expression." (PMID 26560478, 2015). "To further investigate the patho-physiological relevance of IRX2 gene expression in breast cancer, we evaluated IRX2 gene expression in a large publically available patient cohort comprised of 1992 patients." (PMID 26560478, 2015). "To further investigate the significance of IRX2 expression in breast cancer, we evaluated IRX2 expression in a panel of breast cancer cell lines." (PMID 26560478, 2015). "To further explore the possible role for IRX2 in tumor progression, we investigated the ability of IRX2 expression to modify cell migration and proliferation of breast cancer cells." (PMID 26560478, 2015). "The purpose of this study is to gain insights into the significance of IRX2 protein function in the progression of breast cancer." (PMID 26560478, 2015). "In this study we sought to examine the significance of IRX2 expression in the progression of breast cancer." (PMID 26560478, 2015). "In our hands neither transfection of small interfering RNAs nor viral transduction of shRNAs yielded a convenient reduction of IRX2 protein expression in breast cancer cell lines, which has already been reported by other researchers." (PMID 26560478, 2015). "The obtained data provide further evidence for IRX2 as a potential metastasis suppressor as ectopic IRX2 expression diminished secretion of different chemokines and acts as negative regulator of cellular motility of breast cancer cells." (PMID 26560478, 2015).
breast cancer (continued). "Transcription factor IRX2 has been shown to control chemokine expression in breast cancer cells." (PMID 30373633, 2018). "Additionally, constitutive IRX2 over expression was established in BT-549 and Hs578T breast cancer cell lines." (PMID 26560478, 2015). "To experimentally validate the possible role of IRX2 as a metastasis suppressing protein, we initially aimed to study the potential involvement of the IRX2 transcription factor in breast cancer progression using a RNA interference mediated experimental approach." (PMID 26560478, 2015). "Among the inversely correlated genes were four chemokines, CCL5, CXCL9, CXCL10 and CXCL11 indicating that IRX2 might be actively involved in the regulation of chemokine secretion by mediating the transcriptional repression of these chemokines in breast cancer cells." (PMID 26560478, 2015). "Thus, IRX2 could exhibit dual functions in the progression of breast cancer, i.e., in the early stages of tumor development elevated IRX2 expression might contribute to tumor cell proliferation and transformation." (PMID 26560478, 2015). "In line with the suggestion that loss of IRX2 expression might contribute to the onset of tumor cell dissemination, we could show that over expressing of IRX2 markedly reduced the motility of breast cancer cells but did not influence cell proliferation." (PMID 26560478, 2015). "However, in breast cancer (BC), low expression of IRX2 was correlated with tumor staging, lymph node status, negative hormonal receptors status and basal-type primary tumors." (PMID 36980893, 2023). "The possible involvement of IRX2 in cancer development is also supported by the fact that IRX2 may act as a metastasis suppressing protein since its low expression has been found to be correlated with less differentiated and more aggressive breast cancer tumors." (PMID 29568396, 2018). "Furthermore, immunohistochemical staining of 85 breast tumors showed expression of the IRX2 protein in cancerous breast tissue and revealed a significant correlation of IRX2 protein expression only with tumor size, suggesting a possible oncogenic function for the IRX2 protein in breast cancer." (PMID 26560478, 2015). "The analysis of IRX2 mRNA and protein expression in breast cancer cell lines showed that IRX2 expression is absent in the highly aggressive MDA-MB-231, BT-549 and Hs578T cell lines that are all classified to belong to the basal molecular subtype of breast cancer." (PMID 26560478, 2015). "In line with a potential metastasis suppressing function of IRX2, the poorly differentiated, highly metastatic basal breast cancer cell lines MDA-MB-231, Hs578T and BT-549 were completely negative for IRX2 protein expression." (PMID 26560478, 2015).
osteosarcoma (5 papers, 2015 to 2024). A usually aggressive malignant bone-forming mesenchymal neoplasm, predominantly affecting adolescents and young adults. "Elevated EMP1 expression in osteosarcoma tissues is closely associated with lymphatic and distant metastasis, stimulating malignant progression via the IRX2/MMP9 axis." (PMID 40612666, 2024). "In osteosarcoma, increased expression of IRX2 was observed, indicating that it acts as an oncogene that induces proliferation and invasion." (PMID 36980893, 2023). "Controversially, in primary human osteosarcoma tissues, IRX2 expression was observed to be significantly increased in comparison with normal tissues, and was significantly associated with tumor progression and prognosis." (PMID 30760827, 2019). "In vitro assays showed that IRX2 upregulated MMP-9 and VEGF in a PI3K/AKT-dependent manner, and that knockdown of IRX2 in osteosarcoma cell lines inhibited cell proliferation and invasion." (PMID 30760827, 2019). "In osteosarcomas knockdown of IRX2 inhibits cell proliferation and invasion, and elevated IRX2 expression is correlated with worse outcome and age in infant acute lymphoblastic leukemia." (PMID 26560478, 2015). "In osteosarcoma (OS), IRX2 modulates the expression levels of MMP2 and VEGF in an AKT-dependent manner, and overexpression of IRX2 promotes the activation of PI3K/Akt and increases the proliferation and invasiveness of OS cell lines." (PMID 36980893, 2023). "Furthermore, IRX2 promotes the expression of MMP-9 and VEGF through PI3K/Akt signaling activation in osteosarcoma cell lines." (PMID 36980893, 2023).
acute lymphoblastic leukemia (4 papers, 2015 to 2024). Leukemia with an acute onset, characterized by the presence of lymphoblasts in the bone marrow and the peripheral blood. "In contrast, sister homeobox genes IRX2, IRX3 and IRX5 are aberrantly activated in the corresponding malignancies acute myeloid leukemia (AML) and B-cell progenitor acute lymphoid leukemia." (PMID 39689089, 2024). "Moreover, aberrant expression of IRX homeobox genes IRX1, IRX2, IRX3 and IRX5 has been detected in hematopoietic malignancies, including B-cell precursor acute lymphoblastic leukemia (BCP-ALL), T-cell ALL, and some subtypes of acute myeloid leukemia (AML)." (PMID 36833225, 2023). "Furthermore, we identified aberrant expression of IRX2, IRX3 and MEIS1 in patients with B-cell precursor acute lymphoblastic leukemia (BCP-ALL) which originates from early B-cell progenitors." (PMID 36233173, 2022).
acute myeloid leukemia (2 papers, 2023 to 2024). Acute myeloid leukemia (AML) is a group of neoplasms arising from precursor cells committed to the myeloid cell-line differentiation. "On the other hand, the closely related homeobox genes IRX2, IRX3 and IRX5 are aberrantly expressed in subsets of BCP-ALL and acute myeloid leukemia (AML) patients and cell lines." (PMID 39689089, 2024).
colon cancer (2 papers, 2008 to 2012). "LEC3 was up-regulated in MG-thymoma, but down-regulated in colon cancer, Similar to Adenylate cyclase (ADCY2, magnesium ion binding), and the iroquise homeobox gene IRX2, (transcription factor activity)." (PMID 18545673, 2008).
lung adenocarcinoma (2 papers, 2021 to 2022). A carcinoma that arises from the lung and is characterized by the presence of malignant glandular epithelial cells. "Our results signaled that IRX2, SPINK13, and CAPN8 could serve as novel therapeutic targets to prevent tumor growth in lung adenocarcinoma." (PMID 35102706, 2022). "CAPN8, IRX2, and SPINK13 may serve as novel targets of targeted and immune‐based therapies in lung adenocarcinoma." (PMID 35102706, 2022). "The present study uncovered that high expression of IRX2, SPINK13, and CAPN8 could facilitate tumor progression in LUAD with multiple lung adenocarcinoma cell lines." (PMID 35102706, 2022).
lung carcinoma (2 papers, 2018 to 2021). "The following literature review confirmed that six of the nine TFs, including E2F8, MEIS, E4F1, BRCA1, GATA6, and IRX2, play essential roles in lung cancer progression." (PMID 29303984, 2018).
Parkinson disease (2 papers, 2020 to 2025). A progressive degenerative disorder of the central nervous system characterized by loss of dopamine producing neurons in the substantia nigra and the presence of Lewy bodies in the substantia nigra and locus coeruleus. "Irx2, another gene listed, is a transcription factor that has been found to possibly serve as a biomarker for Parkinson’s disease." (PMID 41226761, 2025).
atrophic gastritis (1 paper, 2023). "Downregulation of IRX2 was also observed in H. pylori-positive atrophic gastritis compared with normal gastric mucosal tissues, and in the comparison between Helicobacter pylori-positive atrophic gastritis and Helicobacter pylori-positive GC, it was found to be upregulated." (PMID 36980893, 2023).
brain cancer (1 paper, 2025). A primary or metastatic malignant neoplasm affecting the brain. "Among the other transcription factors that we found among colon transcriptomics features Irx2, Pou4f1, Pou6f1, Tfap2a, Ctdp1, and Msx1 are known to be involved in neuronal development or closely related processes 31–37, and Fubp1 in brain cancer." (PMID 40791429, 2025).
breast tumors (1 paper, 2015). "Taken together these analyses clearly show that low IRX2 expression is correlated with different parameters of poor prognosis, indicating that loss of IRX2 expression is associated with less differentiated and more aggressive breast tumors." (PMID 26560478, 2015). "We previously found that low IRX2 gene expression in primary breast tumors is associated with the presence of DTCs in the bone marrow." (PMID 26560478, 2015). "Using expression profiling on early stage primary breast tumors, low IRX2 expression was previously shown to be associated with the presence of DTCs in the bone marrow, suggesting a possible role of IRX2 in the early steps of metastasis formation." (PMID 26560478, 2015). "We originally identified low IRX2 to be part of gene signature associated with the presence of DTCs in the bone marrow in patients with luminal breast tumors." (PMID 26560478, 2015). "On the other hand, we found that high IRX2 mRNA expression correlates with different parameters that define well differentiated breast tumors and good clinical outcome, like positive hormone receptor status as well as low tumor stage and grade." (PMID 26560478, 2015). "We found that in particular the expression of several chemokines is inversely correlated with IRX2 expression in breast tumors." (PMID 26560478, 2015). "The obtained results show that low expression of the IRX2 transcription factor occurs mainly in less differentiated, basal breast tumors." (PMID 26560478, 2015). "Low IRX2 mRNA expression was found to correlate with high tumor grade, positive lymph node status, negative hormone receptor status, and basal type of primary breast tumors." (PMID 26560478, 2015).
cardiac hypertrophy (1 paper, 2023). "The decreased secretion of myofibroblasts-derived pro-hypertrophic factors (TGF-β, PDGF-A and PDGF-B) in mice with myofibroblast-specific Irx2 depletion in response to Ang II infusion might explain the improvement in cardiac hypertrophy and systolic function." (PMID 37587150, 2023). "In our study, we also found that myofibroblast-specific Irx2 depletion, but not cardiomyocyte-specific Irx2 depletion, could attenuate cardiac hypertrophy, and improve cardiac systolic function." (PMID 37587150, 2023).
cardiomyopathy (1 paper, 2017). A disease of the heart muscle or myocardium proper. "Irx4 knock out mice demonstrated cardiomyopathy with compensated increased Irx2 expression." (PMID 28430825, 2017).
diabetes (1 paper, 2017). "Signature genes included previously reported beta-specific genes like NKX6-1, DLK1, and ADCYAP1 (right) and alpha cell–specific genes like IRX2, LOXL4, and DPP4, a cell surface receptor and diabetes drug target." (PMID 27864352, 2017).
fibrosis (1 paper, 2023). the formation of excess fibrous connective tissue in an organ or tissue in a reparative or reactive process. "The use of Col1α2-driven Irx2 deletion didn’t compromise our main finding that IRX2 is a master regulator of pathological cardiac fibrosis." (PMID 37587150, 2023). "In summary, this study identified IRX2 as a critical regulator of cardiac fibrosis via the transcriptional activation of EGR1." (PMID 37587150, 2023).
gastric cancer (1 paper, 2023). A primary or metastatic malignant neoplasm involving the stomach. "IRX2 was identified together with other genes as a GC immune-related transcription factor (IRTF) in a complex analysis of 1136 gastric cancer samples, in which IRTF regulation patterns were associated with clinical phenotypes, tumor immune microenvironment, immunogenicity and prognosis in GC." (PMID 36980893, 2023). "IRX2 was found to be an important transcription factor that was downregulated in a regulatory network study of 210 gastric cancer tissues and 118 normal tissue samples." (PMID 36980893, 2023). "Interestingly, the expression status of IRX2 was upregulated in early gastric cancer (EGC) compared with low-grade intraepithelial neoplasia (LGIN), one of the last stages of precancerous lesions, in a study of hub genes regulating EGC in a Chinese (Qinghai) population." (PMID 36980893, 2023).
leukaemia (1 paper, 2023). "In our study, IRX2 did not affect Ang II-induced CF proliferation, which was consistent with a previous report demonstrating that IRX2 promoted leukaemia cell differentiation without affecting cell proliferation." (PMID 37587150, 2023).
nasopharyngeal carcinoma (1 paper, 2022). A carcinoma arising from the nasopharyngeal epithelium. "Elevated expression of IRX2 was linked with shorter OS in nasopharyngeal carcinoma (NPC)." (PMID 36505456, 2022).
osteoarthritis (1 paper, 2016). A noninflammatory degenerative joint disease occurring chiefly in older persons, characterized by degeneration of the articular cartilage, hypertrophy of bone at the margins and changes in the synovial membrane. "As IRX2 is strongly expression in human primary osteoblasts of the skeleton, its putative roles in SPP1 regulation in osteoarthritis and osteoporosis are worthy of investigation." (PMID 28105936, 2016).
ovarian carcinoma (1 paper, 2025). A malignant neoplasm originating from the surface ovarian epithelium. "RNA sequencing of ovarian carcinoma-TA-MSCs identifies a distinct predictive algorithm comprising six genes: Annexin A8-like protein 2 (ANXA8L2), Collagen Type XV Alpha 1 Chain (COL15A1), Cytokine Receptor Like Factor 1 (CRLF1), GATA Binding Protein 4 (GATA4), Iroquois Homeobox 2 (IRX2), and TGF‐β2." (PMID 40676710, 2025).
renal failure (1 paper, 2021). "This tissue overlap is also consistent with loci including rs2004187 (IRX2), which is associated with renal failure." (PMID 33979322, 2021).